SLC12A7 (solute carrier family 12 member 7)
Description:
Mediates electroneutral potassium-chloride cotransport when activated by cell swelling. May mediate K(+) uptake into Deiters' cells in the cochlea and contribute to K(+) recycling in the inner ear. Important for the survival of cochlear outer and inner hair cells and the maintenance of the organ of Corti. May be required for basolateral Cl(-) extrusion in the kidney and contribute to renal acidification (By similarity).
Synonyms: KCC4; DKFZP434F076
Tractability: Small molecule: it belongs to a druggable protein family. Antibody: UniProt places it where antibodies can reach, with high confidence; its Gene Ontology location is reachable by antibodies, with high confidence; UniProt predicts a signal peptide or a membrane-spanning region. PROTAC: ubiquitination databases record sites on it; its protein half-life has been measured.
Gene: Protein-coding gene on chromosome 5 (1,050,384 to 1,155,916, reverse strand). Ensembl gene ENSG00000113504.
Subcellular location: Cell membrane
Subcellular location (Human Protein Atlas): Cytosol
Pathways (Reactome):
Transport of small molecules: Cation-coupled Chloride cotransporters
Gene Ontology:
Molecular function: potassium:chloride symporter activity; chloride:monoatomic cation symporter activity; protein kinase binding; transmembrane transporter activity
Biological process: chloride transmembrane transport; chloride transport; potassium ion import across plasma membrane; potassium ion transmembrane transport; cellular response to glucose stimulus; monoatomic ion transport; transmembrane transport
Cellular component: plasma membrane; protein-containing complex; apical plasma membrane; membrane
Genetic constraint (gnomAD): Loss-of-function variants: 96 observed, 110.91 expected, observed/expected ratio (o/e) 0.87, 90% interval 0.73 to 1.03. The upper end of that interval is the gene's LOEUF score, 1.03, which puts it in group 4 of 6, group 1 being the genes least tolerant of losing a copy. Missense variants: 1,358 observed, 1,485.2 expected, observed/expected ratio (o/e) 0.91, 90% interval 0.87 to 0.96. Synonymous variants: 758 observed, 666.29 expected, observed/expected ratio (o/e) 1.14, 90% interval 1.07 to 1.21.
Gene-disease validity (ClinGen):
ClinGen rates the evidence that SLC12A7 causes each of these diseases.
renal tubular acidosis, distal, 2, with progressive sensorineural hearing loss (inheritance undetermined): No Known Disease Relationship.
Homologues: Orthologues: macaque SLC12A7 (96% identical), chimpanzee SLC12A7 (95% identical), mouse Slc12a7 (91% identical), guinea pig SLC12A7 (90% identical), rat Slc12a7 (90% identical), pig SLC12A7 (88% identical), dog SLC12A7 (87% identical), zebrafish slc12a7b (76% identical), zebrafish slc12a7a (71% identical), Drosophila melanogaster kcc (53% identical), Caenorhabditis elegans kcc-2 (46% identical), Drosophila melanogaster Ncc69 (25% identical), and 3 more. Paralogues in human: SLC12A5 (73% identical), SLC12A4 (69% identical), SLC12A6 (69% identical), SLC12A2 (27% identical), SLC12A1 (27% identical), SLC12A3 (26% identical), SLC12A9 (24% identical), SLC12A8 (14% identical).
Diseases named in the same sentence as SLC12A7 in open-access papers:
SLC12A7 is named in the same sentence as 23 diseases in open-access papers, as found by Europe PMC text mining. Sharing a sentence is not in itself a finding about the gene and the disease. The quoted sentences say what the papers report.
adrenocortical carcinoma (4 papers, 2018 to 2026). "Recent studies have shown recurrent gene amplifications and overexpression of SLC12A7 in adrenocortical carcinoma (ACC)." (PMID 29884238, 2018). "The SLC12A7 (or KCC4) has a potassium/chloride symporter activity, and systematic gene amplification was observed in adrenocortical carcinoma, where it promotes higher cell motility and invasiveness." (PMID 37295717, 2023).
ovarian carcinoma (4 papers, 2012 to 2020). A malignant neoplasm originating from the surface ovarian epithelium. "In the ovarian cancer cell line OVCAR-3, SLC12A7 co-localizes with EZR at the cell surface promoting cell motility and potentially modulating extra-cellular interactions." (PMID 29884238, 2018).
breast carcinoma (2 papers, 2018 to 2020). "SLC12A7 is overexpressed in gynecological and breast cancers and overexpression of SLC12A7 and other SLC12 gene family members has been shown to be associated with local tumor invasion, lymph node metastases, and poor clinical outcomes." (PMID 29884238, 2018).
adrenal cancers (1 paper, 2018). A carcinoma involving a adrenal gland. "Using two well-studied adrenal cancer cell lines, one with very low expression of SLC12A7 (SW-13 cells), and one with very high expression of SLC12A7 (NCI-H295R cells), we addressed these questions in this study." (PMID 29884238, 2018). "Moreover, experiments showed that SLC12A7 promotes the malignant behavior of adrenal cancer cells by changing their cell membrane attachment kinetics and consequently, accelerates their invasive behavior." (PMID 29884238, 2018). "In conclusion, this study demonstrates that SLC12A7 plays an important role in adrenal cancer by promoting tumor invasion, and as such, could represent a marker of tumor aggressiveness to serve as a potential therapeutic target." (PMID 29884238, 2018). "However, no studies have been performed to test whether SLC12A7 is involved in promoting adrenal cancers, and if so, the mechanisms behind its potential effect." (PMID 29884238, 2018).
adrenal tumors (1 paper, 2023). "Previous studies showed that SLC12A7 copy gains may serve as a putative molecular indicator of malignancy in indeterminate adrenal tumors, including a marker of malfunctioning tumors." (PMID 37639552, 2023).
autism (1 paper, 2019). Persistent deficits in social interaction and communication and interaction as well as a markedly restricted repertoire of activity and interest as well as repetitive patterns of behavior. "Strikingly, no SLC12A7 CNVs were detected in 60,706 subjects in the ExAC Browser as well as 1,789 control trios comprising parents and unaffected siblings of autism probands from the Simons Simplex Collection previously analyzed." (PMID 31393094, 2019).
diabetes (1 paper, 2021). "FcER1, ITGAX, SLC12A7 are a few of the top 30 significant genes, whose expression increased with the severity of diabetes." (PMID 34925339, 2021). "Microarray analysis of the PBMC dataset (Cohort 1), identified FcER1, TRPC3, SNX20, FAM20A, and SLC12A7 as genes showing increased expression with the severity of diabetes." (PMID 34925339, 2021).
gastric cancer (1 paper, 2020). A primary or metastatic malignant neoplasm involving the stomach. "It has been reported that amplification of SLC12A7 is mainly within HER2− patient samples in gastric cancer, while the precise mechanism of SLC12A7 is still unknown." (PMID 32848739, 2020).
thyroid carcinoma (1 paper, 2026). "Three gene fusions, previously reported only in nonthyroid malignancies (BRAF-TRIM24, SLC12A7-TERT, PVT1-MYC), were described for the first time in thyroid carcinoma." (PMID 41492106, 2026).
cancer (8 papers, 2010 to 2026). A tumor composed of atypical neoplastic, often pleomorphic cells that invade other tissues. "Altered expression of Solute Carrier Family 12 Member 7 (SLC12A7) is implicated to promote malignant behavior in multiple cancer types through an incompletely understood mechanism." (PMID 29884238, 2018). "In this context, elevated expression of SLC12A7 promotes cancer invasion and metastasis through modulation of MMP-2 activity and cell volume control." (PMID 33461589, 2021). "However, it has also been demonstrated that amplified expression of SLC12A7 promotes the malignant behavior of several different cancer types." (PMID 29884238, 2018). "Clonogenic survival and growth are hallmarks of malignant tumors and we tested whether overexpression of SLC12A7 impacted ACC clonogenic growth potential." (PMID 29884238, 2018). "The membrane transporter ABCC1 (MRP1), which confers multidrug resistance to cancer cells, was also enriched in the Panc-1 library, along with three other SLC transporters, SLC4A2, SLC30A1, and SLC12A7 (KCC4), plus the epidermal growth factor receptor EGFR and lipid transport protein ESYT2." (PMID 37295717, 2023). "In the present study, we show a similar role for SLC12A7 in promoting cancer cell migration and invasion, phenotypic hallmarks of aggressive cancers, in two well-characterized ACC cell lines, without any significant impact on cell growth or clonogenic potential." (PMID 29884238, 2018).
tumor (4 papers, 2010 to 2021). "However, determination of a likely association of SLC12A7 amplifications with tumor stage, invasiveness, and survival needs to be explored in a larger cohort." (PMID 29884238, 2018). "Previous studies also have shown a clear role for SLC12A7 in promoting in vitro tumor cell invasion." (PMID 29884238, 2018). "Previous studies have demonstrated that SLC12A7 promotes tumor cell metastasis, in part, by stimulating cell migration and invasion." (PMID 29884238, 2018). "We recently demonstrated moderate expression of SLC12A7 in normal adrenal gland tissue with amplified expression levels observed in ACC tumor samples, suggesting a potential role for SLC12A7 overexpression in ACC tumorigenesis or malignant progression." (PMID 29884238, 2018). "In the same study, the authors also demonstrated that SLC12A7 activity, in part, promoted in vivo tumor growth in SCID mice." (PMID 29884238, 2018). "In conclusion, this study demonstrates that SLC12A7 amplification may promote tumor cell migration and invasion in ACC, at least in part by modulating cell membrane organization and perturbed osmotic signaling." (PMID 29884238, 2018). "Thus, SLC12A7 could represent a molecular marker of ACC tumor aggressiveness and may serve as a potential therapeutic target." (PMID 29884238, 2018).
SLC12A7 also shares sentences with these, for which no sentence is quoted: cervical carcinoma (4 papers); renal tubular acidosis (3); Acidosis (2); deafness (2); infection (2); aneurysm (1); cardiovascular disease (1); glioma (1); hepatocellular carcinoma (1); lung carcinoma (1); metabolic acidosis (1); neurodegenerative disease (1).